SMAD4 (SMAD family member 4)
Diseases named in the same sentence as SMAD4 in open-access papers (continued):
Sharing a sentence is not in itself a finding about the gene and the disease.
B-cell lymphoma (2 papers, 2019 to 2021). "In 2001, SMAD3 and its homolog, SMAD4, have been shown to mediate the expression of autoimmune antibodies during B-cell lymphoma." (PMID 34899868, 2021). "Moreover, in Raji/ADM cells (B-cell non-Hodgkin’s lymphomas), inhibiting the activation of TGFβ signaling pathway via silencing Smad4 contributes to the suppression of cell viability, invasion and migration." (PMID 31694672, 2019).
basal cell carcinoma (2 papers, 2021). A carcinoma involving the basal cells. "KEGG analysis also highlights several pathways associated with disease including “basal cell carcinoma” (Wnt6, Gli2, Wnt10a) and “htlv-i infection” (Smad4, Wnt10a, Prkacb, Wnt6, Tgfbr2) in M. spretus." (PMID 34794440, 2021).
bone metastasis (2 papers, 2011 to 2015). Transfer of a neoplasm from its primary site to bones. "Almost all patients with only bone metastasis expressed SMAD4 either in the cytoplasm or the nucleus." (PMID 26040677, 2015). "Therefore, c.1350G > A could represent a potential prognostic marker as SMAD4 expression has been shown to be an important mediator in the development of osteolytic bone metastasis in late cancer stages but is not required in its maintenance or progression." (PMID 21835029, 2011).
Cachexia (2 papers, 2016 to 2022). Severe weight loss, wasting of muscle, loss of appetite, and general debility related to a chronic disease. "The Smad4 tKO NOD mice showed symptoms of a wasting syndrome; they were disheveled with hunched backs, swollen feet, dry tail skin, scruffy hair and died between 8 and 9 months of age." (PMID 27880731, 2016).
Cerebral ischemia (2 papers, 2013 to 2020). Restriction of arterial blood supply to the brain associated with insufficient oxygenation to support the metabolic requirements of the tissue. "There were 198 TFs identified after 6 h MCAO operation, and six TFs (Sox2, Smad3, FoxO1, Creb1, Egr,1 and Smad4) were considered as critical TFs in response to cerebral ischemia." (PMID 33414894, 2020).
cervical adenocarcinoma (2 papers, 2020 to 2022). An adenocarcinoma arising from the cervical epithelium. "However, the expression of TGF-β1 and SMAD4 proteins was elevated in cervical adenocarcinoma tissues and cervical squamous carcinoma." (PMID 32596357, 2020).
cervical squamous cell carcinoma (2 papers, 2013 to 2017). A squamous cell carcinoma arising from the cervical epithelium. "An immunohistological study in cervical squamous cell carcinomas revealed a significant correlation of weak cytoplasmic Smad4 staining with both the presence of positive lymph nodes and recurrent disease." (PMID 24047375, 2013). "This implies that somatic alterations in TGFBR2, CREBBP, and SMAD4 may be cervical squamous cell carcinoma-specific, although E7-driven expression effects in the TGFβ pathway may still play a role in carcinogenesis in other HPV-positive cancers." (PMID 28771191, 2017). "However, Smad4 expression is decreased or lost in 90% of cervical squamous cell carcinomas." (PMID 24047375, 2013).
chronic myeloid leukemia (2 papers, 2015 to 2025). "A humanized IgG4 antibody, h4#147D, demonstrated antitumor efficacy by inducing stress response signals (e.g., JNK, p38MAPK), SMAD4 expression, and caspase-3 activation in cancer models such as pancreatic ductal adenocarcinoma (PDAC), HCC, and chronic myeloid leukemia (CML)." (PMID 40265417, 2025).
clear cell renal cell carcinoma (2 papers, 2019 to 2021). "Binding targets of SUZ12 and EZH2 were consistently enriched across all five cancer types, while targets of REST and SMAD4 were enriched in all cancers except for clear cell renal cell carcinoma." (PMID 31523055, 2019).
Cognitive impairment (2 papers, 2019 to 2023). Abnormal cognition is characterized by deficits in thinking, reasoning, or remembering. "These dysregulations can result in compromised brain function, and mutations in TGFβRI and SMAD4 can result in cognitive impairment among other mental disorders." (PMID 31829243, 2019). "To evaluate whether Smad7 is involved in the occurrence of cognitive impairment after anesthesia and surgery by regulating the TGF-β1-related signaling pathway, we detected the protein expression of Smad2/3, Smad4 and phosphorylated Smad2/3 in the hippocampus in wild-type mice and Smad7−/− mice." (PMID 37507781, 2023).
coronary artery disease (2 papers, 2024). "Meanwhile, the mechanism of action of MiR-145-5p involves mitigating hypoxia/reoxygenation-induced damage to cardiac microvascular endothelial cells in coronary artery disease by inhibiting Smad4 expression." (PMID 39680523, 2024). "MiRNA-145-5p levels decreases in patients with coronary artery disease, while its overexpression effectively alleviates H/R-induced CMEC injury by inhibiting mothers against decapentaplegic homolog 4 (SMAD4)." (PMID 38545341, 2024).
deafness (2 papers, 2016 to 2022). An inherited or acquired condition characterized by the complete loss of the ability to hear from one or both ears. "This confirms the role of SMAD4 in the development of the inner ear and partly explains the development of deafness in some patients with MS." (PMID 35907855, 2022).
dissection (2 papers, 2020 to 2023). The separation and isolation of tissues for surgical purposes, or for the analysis or study of their structures. "Heald and colleagues observed cardiac pathologies in 6/16 SMAD4 + JPS-HHT patients, while Wain and colleagues reported 7/34 JPS patients had connective tissue defects including enlarged aortic root, aortic and mitral valve insufficiency and aortic dissection." (PMID 38066625, 2023).
echinococcosis (2 papers, 2022 to 2026). A parasitic infection caused by tapeworm larvae of Echinococcus. "The expression levels of TGF-β, SMAD2, SMAD3, SMAD4, and leukemia inhibitory factors (LIF) in the cystic fluid and the corresponding paracystal tissues of infected viscera or tissues in children with hydatidosis were measured using the ELISA kit." (PMID 36443650, 2022).
Ewing sarcoma (2 papers, 2020 to 2024). A small round cell tumor that lacks morphologic, immunohistochemical, and electron microscopic evidence of neuroectodermal differentiation. "Of the priority candidates, 6 were found with enriched dependency in Ewing Sarcoma cell lines (AKT1, BARD1, HSP90AA1, NCOA1, SETDB1, SMAD4)." (PMID 38177639, 2024).
female infertility (2 papers, 2022 to 2024). Diminished or absent ability of a female to achieve conception. "Previous mouse model studies have shown that deletion of SMAD4 and FOXL2 in GnRH results in FSH deficiency and female infertility, and FSH and LH can enhance the activity of the TGF-β/SMAD signaling pathway." (PMID 35326436, 2022). "In mouse gonadotropes, deletion of Smad4 led to FSH deficiency and female subfertility." (PMID 39080808, 2024).
fibrosarcoma (2 papers, 2016 to 2024). A malignant mesenchymal fibroblastic neoplasm affecting the soft tissue and bone. "The expression of TGFBR1 in NK cells can enhance cancer cell metastasis and accelerate the growth of fibrosarcoma, indicating that TGF-β activates SMAD4 to inhibit NK cell-mediated monitoring in cancer metastasis." (PMID 38514720, 2024).
gallbladder cancer (2 papers, 2025). "The results highlight the crucial role of the TGF-β/SMAD4 signaling pathway in regulating vital cellular processes in cancer growth and suggest potential therapeutic options for targeting this pathway in gallbladder cancer." (PMID 40422217, 2025).
hamartoma (2 papers, 2019 to 2023). A benign and excessive tumor-like growth of mature cells and normal tissues which grow in a disorganized pattern. "Homozygous knock-out of the Smad2 and Smad4 genes was embryonic lethal; however, deletion of one Smad4 allele only yielded gastrointestinal hamartomas in the stomach and duodenum with histopathological features reminding of JPS." (PMID 31614493, 2019). "Some genes are involved in the pathogenesis of hamartoma development, including SMAD4, PTEN, STK1, and BMPR1A." (PMID 36923765, 2023).
Hepatic steatosis (2 papers, 2021 to 2025). Steatosis is a term used to denote lipid accumulation within hepatocytes. "Additionally, they reported that deletion of SMAD4 in NASH mice models showed decreased hepatic steatosis, inflammation, liver cell apoptosis and nonalcoholic fatty liver activity score compared with wild-type mice." (PMID 34202571, 2021). "MYCBP2 inhibits signaling pathways that drive hepatic steatosis, including mTOR and p38 MAPK, while also suppressing adipogenesis by promoting SMAD4 ubiquitination, possibly explaining why aggregated deleterious variants in MYCBP2 were positively associated with both MASLD and body fat percentage." (PMID 40065360, 2025).
hepatitis B (2 papers, 2021 to 2023). "It has also been shown that miR-125b is associated with hepatitis B and has been targeted with genes that include IL6, DDX3X, STAT2, STAT3, SMAD4, CDKN1B, MAP3K1 and so on from our results." (PMID 34988221, 2021).
ileum (2 papers, 2023 to 2024). "Our findings indicated a higher proportion of SMAD4 mutation in duodenal cancer patients in comparison to those with jejunum or ileum cancers." (PMID 37974218, 2023).
Loeys-Dietz syndrome (2 papers, 2020 to 2024). Loeys-Dietz syndrome is a rare genetic connective tissue disorder characterized by a broad spectrum of craniofacial, vascular and skeletal manifestations with four genetic subtypes described forming a clinical continuum. "We did not identify any mutations of HTAD genes that cause Loeys-Dietz syndrome, which is associated with early onset TAD and BAV, and a total of three causal mutations in non-syndromic HTAD genes (a glycine substitution in FBN1 and loss of function mutations in SMAD4 and FOXE3)." (PMID 38370698, 2024).
medulloblastoma (2 papers, 2015 to 2023). A malignant, invasive embryonal neoplasm arising from the cerebellum. "The results showed that Smad2 + 3, Smad4, Bcl2, and Caspase3 expression was changed in SHH medulloblastoma cell lines DAOY regardless of overexpression or knockdown of VASH2, indicating that VASH2 expression in myeloblasts may be mediated by affecting downstream indicators of TGFβ pathway." (PMID 37821528, 2023).
microcephaly (2 papers, 2017 to 2021). A congenital or acquired developmental disorder in which the circumference of the head is smaller than normal for the person's age and sex. "Tcf4 binds together with microcephaly-associated transcription factors Smad4, Sox2, Chd7 and Ep300 to active enhancers at primary microcephaly genes Mcph1 and Wdr62." (PMID 28375211, 2017). "Moreover, Tcf4 protein interacts with 10 transcriptional regulators associated with microcephaly, including Smad4." (PMID 28375211, 2017). "Tcf4 binds with a number of its interaction partners to primary microcephaly genes and (at least) Tcf4 and Smad4 also regulate such genes, providing an explanation for their shared microcephaly phenotype." (PMID 28375211, 2017).
multiple sclerosis (2 papers, 2017 to 2020). A progressive autoimmune disorder affecting the central nervous system resulting in demyelination. "These miRNAs negatively regulated the TGFβ pathway (TGFBR1 and SMAD4 were significantly reduced in patients with multiple sclerosis), resulting in a decreased capacity of naive CD4 T cells to generate regulatory T cells." (PMID 32973667, 2020).
neuroendocrine tumor (2 papers, 2019 to 2021). "Correspondence between the site of SMAD4 mutation and tumor morphology was demonstrated directly in a case of mixed adenocarcinoma and neuroendocrine tumor (Case #20)." (PMID 30730996, 2019).
Pancreatoblastoma (2 papers, 2018 to 2024). A rare malignant epithelial neoplasm arising from the pancreas.
papillary thyroid cancer (2 papers, 2013 to 2018). "We recently demonstrated that a Smad4 mutation, Smad4 C324Y, isolated from nodal metastases of papillary thyroid carcinoma, causes an increase of TGF-β signaling, responsible for the acquisition of transformed phenotype and invasive behaviour in thyroid cells stably expressing this mutation." (PMID 23591524, 2013). "We recently demonstrated that a Smad4 mutation, Smad4 C324Y, isolated from nodal metastases of papillary thyroid carcinoma, causes an increase of TGF-β signaling responsible for the acquisition of transformed phenotype and invasive behaviour in thyroid cells stable expressing this mutation." (PMID 23591524, 2013). "We have recently demonstrated that a Smad4 mutation, Smad4 C324Y, isolated from nodal metastases of papillary thyroid carcinoma, determines a significant increase of TGF-β signaling, causing the acquisition of transformed phenotype and invasive behaviour when stably expressed in thyroid cells." (PMID 23591524, 2013). "Absent or decreased expression of Smad4 has been demonstrated in various cancers, including pancreatic, colorectal, head and neck, and, more recently, in papillary thyroid carcinomas (PTCs), suggesting that the TGF-β signaling functions as a tumor suppressor." (PMID 23591524, 2013).
rectal adenocarcinoma (2 papers, 2023 to 2024). "Most commonly gained or lost genes seen in rectal adenocarcinoma (FLT3, CDX2, GNAS, BCL2, SMAD4, MALT1) are not found in rectal squamous cell carcinoma." (PMID 36357817, 2023).
Sepsis (2 papers, 2021 to 2024). Sepsis is defined as life-threatening organ dysfunction caused by a dysregulated host response to infection. "SMAD4 has been linked to the regulation of intercellular tight junction by increasing expression of junctional adhesion molecule (JAM-3) during sepsis." (PMID 34646379, 2021). "During sepsis, active TGF-β1 is released and attached to its receptor (TGFβI/II) resulting in the phosphorylation and activation for Smad2/3, which binds with Smad4, leading to the formation of an active complex of Smad2/3/4." (PMID 38926458, 2024).
Skeletal myopathy (2 papers, 2017 to 2018). "Inhibition of Smad4 SUMOylation impaired spatial learning and memory in rats by downregulating TPM2, a gene associated with skeletal myopathies." (PMID 29183317, 2017).
urothelial bladder cancer (2 papers, 2019 to 2021). "We evaluated the association of TGF-β1, Smad2, and Smad4, the key components of canonical TGFβ pathway, with clinicopathologic characteristics of urothelial bladder cancer, and assessed their prognostic value in prediction of patients’ outcome." (PMID 31238579, 2019). "Materials and Methods: Immunohistochemical analysis of TGF-β1, Smad2, and Smad4 expression was performed on 404 urothelial bladder cancer samples, incorporated in tissue microarrays." (PMID 31238579, 2019).
urothelial carcinoma (2 papers, 2014 to 2019). A malignant neoplasm derived from the transitional epithelium of the urinary tract (urinary bladder, ureter, urethra, or renal pelvis). "Smad4 staining was observed in both, cytoplasm and nucleus of urothelial carcinoma." (PMID 31238579, 2019).
villous adenoma (2 papers, 2024 to 2025). An epithelial neoplasm morphologically characterized by the presence of a villous architectural pattern. "Loss of SMAD4 suggests impairment of the TGF-β-mediated growth inhibitory pathway, potentially accelerating oncogenesis; notably, the loss rate of SMAD4 was relatively high (75%) in villous adenoma patients." (PMID 40919165, 2025).
abdominal aortic aneurysm (1 paper, 2021). Enlargement and ballooning of the vessel that supplies arterial blood to the abdomen, pelvis and legs. "The findings of this study show that downregulation of SNHG5 increases expression levels of mir‐205‐5p and inhibits SMAD4 expression, thus affecting the function of vascular smooth muscle in abdominal aortic aneurysm." (PMID 34185955, 2021).
abortion (1 paper, 2017). the ending of pregnancy by removing a fetus or embryo before it can survive outside the uterus. "Collectively, the findings suggested that ESA restricted Foxp3 expression by inhibiting TGFßRII/Smad2/Smad3/Smad4 signalling, ultimately resulting in abortion." (PMID 28300338, 2017).
acute pancreatitis (1 paper, 2014). An acute inflammatory process that leads to necrosis of the pancreatic parenchyma. "Similarly, lungs from both sham controls and acute pancreatitis-associated ALI showed moderate levels of Smad4 in bronchial epithelial, vascular endothelial and infiltrating cells." (PMID 24688224, 2014).
alcoholic liver diseases (1 paper, 2023). A disorder caused by damage to the liver parenchyma due to alcohol consumption. "According to our data, miR-183-5p targets FOXO1, SMAD4, and GSK3B genes involved in transcriptional misregulation in cancer, FOXO signaling pathway and alcoholic liver disease." (PMID 37168369, 2023).
ameloblastoma (1 paper, 2024). The most common odontogenic tumor, arising from the epithelial component of the embryonic tooth and usually affecting the molar-ramus region of the mandible or maxilla. "In ameloblastomas, low expression of TGF-β1 and functional pSmad2/3 and Smad4 proteins do not indicate a critical role for the TGF-β pathway." (PMID 38396916, 2024).
anaplastic thyroid cancer (1 paper, 2021). "High levels of SMAD family member 4 (SMAD4) were observed in follicular thyroid cancer, while SMAD family member 7 (SMAD7) was the most expressed transcription factor in anaplastic thyroid cancer." (PMID 34680488, 2021).
Anxiety (1 paper, 2015). Intense feelings of nervousness, tension, or panic often arise in response to interpersonal stresses. "In a previous report, we investigated the effect forebrain-specific loss of Smad4 (fbΔSmad4) on learning, memory, and anxiety, but only observed a modest increase in open-arm exploration in the EPM that was not significantly different than controls." (PMID 26444546, 2015). "In the Elevated Plus Maze, BMPRII mutants and Smad4 mutants showed reduced anxiety, while in exploratory tests, BMPRII mutants showed more interest in object exploration." (PMID 26444546, 2015).
aphakia (1 paper, 2016). "We provide additional evidence that loss of Smad4 in the surface ectoderm leads to varying degrees of microphthalmia with atresia iridis or even aphakia, and defective formation of ciliary body and iris." (PMID 27494603, 2016). "Various degrees of microphthalmia with atresia iridis (appeared in 90% of the cases) or even aphakia (appeared in 10% of the cases) was observed in the Smad4-cKO mutant." (PMID 27494603, 2016). "Taken together, deletion of Smad4 in the ocular surface ectoderm leads to microphthalmia, aphakia and hypoplasia of ciliary body and iris." (PMID 27494603, 2016).
Arrhythmia (1 paper, 2018). Any cardiac rhythm other than the normal sinus rhythm. "Two genes associated with potential polyposis syndromes (SMAD4, BMPR1A) and KCNJ2, associated with arrhythmia phenotypes, were included in the list of genes considered actionable among pediatric populations." (PMID 29301385, 2018).
arteriosclerosis (1 paper, 2020). A vascular disorder characterized by thickening and hardening of the walls of the arteries. "Previous studies also showed that the aggression of arteriosclerosis was due to the sustainment of inflammatory monocytes and the disruption of monocyte homeostasis through the reduction of SMAD4 levels." (PMID 33224271, 2020).